TAF1L (TATA-box binding protein associated factor 1 like)
Description:
May act as a functional substitute for TAF1/TAFII250 during male meiosis, when sex chromosomes are transcriptionally silenced.
Synonyms: TAF(II)210; TAF2A2
Tractability: Small molecule: a structure with a bound ligand is known; a high-quality ligand is known; it has a binding pocket of medium quality. PROTAC: ubiquitination databases record sites on it; a small molecule that binds it is known.
Target class: Epigenetic regulator; Bromodomain; Reader
Chemical probes: BAY-299 (high quality)
Gene: Protein-coding gene on chromosome 9 (32,629,454 to 32,635,669, reverse strand). Ensembl gene ENSG00000122728.
Subcellular location: Nucleus
Pathways (Reactome):
Gene expression (Transcription): RNA Polymerase II Pre-transcription Events; RNA Polymerase II Promoter Escape; RNA Polymerase II Transcription Initiation; RNA Polymerase II Transcription Initiation And Promoter Clearance; RNA Polymerase II Transcription Pre-Initiation And Promoter Opening
Disease: HIV Transcription Initiation; RNA Polymerase II HIV Promoter Escape; Transcription of the HIV genome
Gene Ontology:
Molecular function: histone reader activity; TBP-class protein binding; histone acetyltransferase activity; protein serine/threonine kinase activity; RNA polymerase II general transcription initiation factor activity; DNA binding
Biological process: male meiotic nuclear division; positive regulation of DNA-templated transcription; regulation of transcription by RNA polymerase II; RNA polymerase II preinitiation complex assembly; chromatin organization; chromatin remodeling; DNA-templated transcription initiation; transcription by RNA polymerase II
Cellular component: nucleoplasm; transcription factor TFIID complex; nucleus
Genetic constraint (gnomAD): Loss-of-function variants: 30 observed, 132.33 expected, observed/expected ratio (o/e) 0.23, 90% interval 0.17 to 0.31. The upper end of that interval is the gene's LOEUF score, 0.31, which puts it in group 1 of 6, group 1 being the genes least tolerant of losing a copy. Missense variants: 2,099 observed, 2,347.3 expected, observed/expected ratio (o/e) 0.89, 90% interval 0.86 to 0.93. Synonymous variants: 764 observed, 827.46 expected, observed/expected ratio (o/e) 0.92, 90% interval 0.87 to 0.98.
Homologues: Orthologues: chimpanzee TAF1L (97% identical), dog TAF1 (93% identical), macaque TAF1L (92% identical), rat Taf1 (90% identical), mouse Taf1 (90% identical), tropical clawed frog taf1 (81% identical), zebrafish taf1 (76% identical), Drosophila melanogaster Taf1 (50% identical), Caenorhabditis elegans taf-1 (34% identical). Paralogues in human: TAF1 (92% identical).
Diseases named in the same sentence as TAF1L in open-access papers:
TAF1L is named in the same sentence as 10 diseases in open-access papers, as found by Europe PMC text mining. Sharing a sentence is not in itself a finding about the gene and the disease. The quoted sentences say what the papers report.
metastatic disease (2 papers, 2021 to 2024). "The first subtype encompasses mutations that consistently present in both primary gastric lesions and metastatic tumors, such as RHOA (6 mutations in primary gastric lesions/6 mutations in metastasis tumors) and TAF1L (1/1)." (PMID 38704377, 2024). "For instance, TAF1L is identified as a strong metastatic driver originating during the transition from primary to metastatic disease." (PMID 34771455, 2021).
esophageal squamous cell carcinoma (1 paper, 2023). Esophageal squamous cell carcinoma (ESCC) is a type of esophageal carcinoma (EC) that can affect any part of the esophagus, but is usually located in the upper or middle third. "As for TAF1L, the overexpression promotes cell proliferation, migration, and invasion in esophageal squamous cell carcinoma (ESCC) by modulating the Akt signaling pathway." (PMID 36674511, 2023).
oral squamous cell carcinoma (1 paper, 2020). "This study focused on investigating the relationships of TAF1L expression and clinical features or pathological stages of oral squamous cell carcinoma (OSCC), and its potential roles of TAF1L on OSCC development." (PMID 32174793, 2020). "This study intended to reveal relationships of TAF1L expression with clinical features or pathological stages of oral squamous cell carcinoma." (PMID 32174793, 2020).
tongue cancer (1 paper, 2020). A malignant neoplasm affecting the tongue. "Thus, the detection of TAF1L expression was performed in a panel of OSCC cell lines, such as Ca9-22 (cancerous gingival epithelia) and Tca-8113 (tongue cancer) cells, as appropriate cell lines for further testing." (PMID 32174793, 2020).
cancer (6 papers, 2019 to 2023). A tumor composed of atypical neoplastic, often pleomorphic cells that invade other tissues. "Up until now, only a few research studies have reported that TAF1L mutation is associated with cancer pathogenesis." (PMID 32174793, 2020). "Subsequently, growing studies have reported that deletions, point mutations, abnormal expression and inactivation of TAF1L were involved in the tumorigenesis of several cancers, such as lung, oral, gastric, colorectal, and urothelial cancers 14-17." (PMID 32174793, 2020). "To date, only several studies have analyzed the roles of TAF1 or TAF1L in facilitating cancer development and progression." (PMID 36674511, 2023). "Currently, there is little known regarding the biological functions of TAF1L, especially its pathological effects on cancer." (PMID 32174793, 2020). "Given the close homology between TAF1 and TAF1L, it was hypothesized that TAF1L may have similar regulatory functions in cancer." (PMID 34771455, 2021). "Therefore, a high TAF1L level enhances OSCC development, although a direct mechanistic link to cancer stemness is still missing." (PMID 36674511, 2023). "In cancer researches, although it has known that TAF1 can play important roles on cell proliferation and apoptosis 11, little is known in regards to that is pathophysiological functions of TAF1L." (PMID 32174793, 2020).
tumor (3 papers, 2013 to 2020). "Images of IHC staining demonstrated autophagic marker - LC3 was upregulated slightly, whereas apoptotic marker - Caspase 3 was downregulated in tumor tissues post TAF1L - overexpression treatment in vivo." (PMID 32174793, 2020). "The correlation among TAF1L gene, apoptosis and autophagy related markers in tumor lesions from mouse model was verified by using IHC." (PMID 32174793, 2020).
TAF1L also shares sentences with these, for which no sentence is quoted: colon adenocarcinoma (1 paper); lung squamous cell carcinoma (1); metastasis tumors (1); pulmonary carcinoid tumor (1).